FGF1 (fibroblast growth factor 1)
Diseases named in the same sentence as FGF1 in open-access papers (continued):
Sharing a sentence is not in itself a finding about the gene and the disease.
metabolic disease (11 papers, 2014 to 2026). A congenital disorder (due to inherited enzyme abnormality) or acquired (due to failure of a metabolically important organ) disorder resulting from an abnormal metabolic process. "Building on prior evidence implicating the FGF1/AMPK axis in metabolic disorders, we investigated the impact of circZBTB46 on FGF1 and AMPK." (PMID 41513602, 2026). "Studies have shown that FGF1 reduces blood sugar by increasing insulin sensitivity, providing a new approach for the treatment of metabolic diseases like fatness, NAFLD and T2DM." (PMID 39296548, 2024). "Therefore, potential cardiovascular consequences need to be thoroughly addressed before considering FGF1 as a therapeutic target for metabolic disease." (PMID 41541501, 2026). "While the exact relationship between serum FGF1 levels and metabolic diseases is not fully understood, FGF1 is considered a critical transducer of PPARγ signaling, which is essential for the proper coupling of nutrient storage to adaptive adipose tissue remodeling." (PMID 41520078, 2026). "In addition, FGF1, FGF10, and FGF21 have been shown to be adipokines with crucial roles in WAT or BAT functions, suggesting new roles for FGFs and potential therapeutic strategies for metabolic disorders." (PMID 24605108, 2014).
infection (7 papers, 2013 to 2025). The state of being infected such as from the introduction of a foreign agent such as serum, vaccine, antigenic substance or organism. "Only FGF-1 was increased in early stage infection and other growth factors such as FGF-2 and IGF-1 were highly induced from 14 days after infection." (PMID 24351861, 2013). "However, we did not identify changes in FGF-1 levels after six months of infection or after later convalescence when compared to the control." (PMID 40709999, 2025). "In contrast, infection did not significantly impact cellular expression of EGF, FGF2, and VEGFB, and FGF1 expression was not reliably detected." (PMID 31569536, 2019). "Thus, FGF-1 treatment did not affect the functional capability of CD4 and CD8 T cells at the site of infection." (PMID 34054858, 2021).
cardiovascular disease (4 papers, 2022 to 2026). "Native fibroblast growth factor 1 (FGF1) is known for its anti-oxidative benefits in cardiovascular diseases, but possesses a potential tumorigenic risk." (PMID 36235670, 2022). "Researchers have focused on the therapeutic benefits of FGF-1 in cardiovascular disorders, nerve injury, and wound healing." (PMID 38542166, 2024). "Initially recognized as a mitogen and isolated from bovine pituitary glands, FGF-1 has since been extensively studied and employed in treating cardiovascular disease, nerve damage, and wound healing." (PMID 38542166, 2024). "Therefore, FGF1 has a great prospect of clinical application in cardiovascular disease." (PMID 36235670, 2022).
neurodegenerative disease (2 papers, 2016 to 2024). A disorder of the central nervous system characterized by gradual and progressive loss of neural tissue and neurologic function. "Among the target genes of these miRNAs, we found five upregulated genes in our snRNA-seq dataset are associated with neurodegenerative diseases, including Atcb, Elavl2, and Fgf1, which are associated with ALS." (PMID 38467605, 2024).
brain disorder (1 paper, 2025). A disease affecting the brain or part of the brain. "Sex hormone regulation of FGF1 expression has previously been demonstrated in several tissue types, though not specifically in the context of AD and brain disorders." (PMID 39737748, 2025).
kidney (1 paper, 2012). "It is interesting that while in absence of ischemia, FGF1/Tek mice exhibited release of FGF1 to the circulation, it did not result in kidney pathologies." (PMID 22606265, 2012).
retinopathy (1 paper, 2025). "The intravitreal injection of miR-18a-5p mimic in a mouse model of oxygen-induced retinopathy effectively suppressed retinal neovascularization by targeting key pro-angiogenic factors, FGF1 and HIF1A." (PMID 40002813, 2025).
vasculopathy (1 paper, 2025). "Impaired tissue repair and angiogenesis, involving FGF1, FGF2, TGF-β, VEGF, and HIF-1α, has been implicated in vasculopathy and pseudoaneurysm formation in STAT3-HIES." (PMID 40491905, 2025).
FGF1 also shares sentences with these, for which no sentence is quoted: neurological disease (5 papers); cardiomyopathy (4); idiopathic pulmonary fibrosis (4); Myocardial fibrosis (4); endometrial cancer (3); heart diseases (3); Impaired glucose tolerance (3); injury (3); acute myocardial infarction (2); clear cell Renal Cell Carcinoma (2); cognitive decline (2); dyslipidemia (2); genetic disease (2); keratitis (2); Lyme disease (2); lymphoma (2); major depression (2); non-small cell lung carcinoma (2); pancreatic ductal adenocarcinoma (2); Parkinson’s (2); peripheral nerve injury (2); pressure ulcers (2); retinal ischemia (2); triple-negative breast carcinoma (2); type 1 diabetes (2); viral infection (2); acute myeloid leukemia (1); adenomyosis (1); adult T-cell leukemia/lymphoma (1); age-onset diseases (1).
A further 65 diseases each share a sentence with FGF1 in 1 paper.